IL13 (interleukin 13)
Diseases named in the same sentence as IL13 in open-access papers (continued):
Sharing a sentence is not in itself a finding about the gene and the disease.
atopic dermatitis (continued). "In addition, the expression of IL-4, IL-13, CXCL10, CCL5, CCL17, and CCL22, which are atopic dermatitis mediators, increased 2- or 3-fold in HaCaT cells treated with DPM compared with that in the control group." (PMID 39599592, 2024). "In addition, the gene expression levels of IL-4, IL-13, CXCL10, CCL5, CCL17, and CCL22, which are related to atopic dermatitis, were significantly decreased by HCFE in DPM-stimulated HaCaT cells." (PMID 39599592, 2024). "In addition, in the case of atopic dermatitis, the number of patients decreased further after 2017, the year in which new effective therapeutic options such as anti-IL4 and IL13 biologics and JAK inhibitors for atopic became available." (PMID 38076241, 2023). "The pathogenesis of atopic dermatitis involves various inflammatory cytokines, particularly IL-4 and IL-13, acting on both immune cells and nonimmune cells and enhancing type 2 inflammation." (PMID 37298299, 2023). "The roles of IL-4, IL-13, IL-31, and TSLP in the pathogenesis of atopic dermatitis might involve a dysfunctional epidermal barrier and allergen sensitization, which are characterized by intense itching and pruritus." (PMID 37676892, 2023). "As in atopic dermatitis epidermis, we found no obvious redistribution of E-cadherin throughout the IL-4/IL-13-treated skin." (PMID 37289055, 2023). "As IL-4/IL-13 treatment of epidermal equivalents based on N/TERT-1 cells can induce histopathological and molecular hallmarks of atopic dermatitis, we investigated whether the cytokine-induced barrier alterations enhance HSV-1 invasion." (PMID 37289055, 2023). "Our analysis showed that the IL-4 and IL-13 Reactome pathway was significantly enriched in HS lesional skin compared with HS non-lesional skin, atopic dermatitis, and psoriatic skin." (PMID 38069342, 2023). "Nectin-1 showed no major redistribution in the thickened atopic dermatitis and IL-4/IL-13-treated human epidermis in which HSV-1 can invade." (PMID 37289055, 2023). "Patients with atopic dermatitis show increased expression of Klrg1 and the interaction of activated ILC2s with E-cadherin results in a down regulation of GATA-3, IL-5, IL-13, amphiregulin and reduced ILC2 proliferation; suggesting a negative regulatory role for Klrg1 in skin ILC2s." (PMID 34759931, 2021). "Smits and colleagues established psoriasis and atopic dermatitis models using N/TERT epidermal skin by adding Th1/Th17 (TNF-α, IL-6, IL-1α, IL-17, and IL-22) cytokines and Th2 (IL-4 and IL-13) cytokines, respectively, during the final stage of the skin maturation." (PMID 32509598, 2020). "Lastly, medically targeted cytokines known to drive inflammatory skin diseases such as psoriasis (IL-17, IL-22, and IL-23) and atopic dermatitis (IL-4, IL-5, IL-13) were not identified in healthy skin." (PMID 33154365, 2020). "Overexpression of IL-4 and IL-13 in the skin seems not to be sufficient for the induction of a fully developed atopic dermatitis phenotype." (PMID 23531535, 2013). "In addition, ingestion of FFO markedly reduced IL-13 and IFN-γ levels and increased the expression of specific Treg cells markers (TGF-β and Foxp3) compared with NFO group in DNCB-stimulated atopic dermatitis mice model." (PMID 22873180, 2012). "The immunomodulatory effects of probiotics can reduce the severity of atopic dermatitis by inhibiting Th2 cell responses, cytokines such as IL-4, IL-5, IL-6, and IL-13 are no longer secreted, INF-γ (cytokines released by Th1 cells) is decreased, phagocytosis is stimulated, and serum IgA increases." (PMID 39781533, 2025). "Aside from filaggrin, loricrin and involucrin are also downregulated by IL-4 and IL-13 in lesional and non-lesional atopic dermatitis skin, contributing to a defective skin barrier that allows penetration of bacteria and allergens into the skin, leading to infections and allergen sensitization." (PMID 39202657, 2024).
atopic dermatitis (continued). "SCORAD: scoring atopic dermatitis index, MRSA: methicillin-resistant S. aureus, NB-UVB: narrowband ultraviolet B, EASI: Eczema Area and Severity Index, CFU: colony-forming units, TCS: topical corticosteroid, TISS: Three-Item Severity Score, IL-13: interleukin-13, ShA9: S." (PMID 38024036, 2023). "A completely human anti-IL-13 monoclonal antibody called tralokinumab has been licensed for use in Europe and the United States to treat individuals with moderate to severe atopic dermatitis who are not satisfactorily managed by topical prescription treatments." (PMID 36983094, 2023). "Given increased levels of type 2 cytokines, IL-13, IL-4 and IL-5, in acute atopic eczema lesions and enhanced production of epithelial cytokines IL-33, IL-25 and TSLP, it is plausible that group 2 innate lymphoid cells contribute to the pathogenesis of atopic dermatitis." (PMID 25427661, 2014). "Based on our findings it may be inferred that dogs with atopic dermatitis manifest skin lesions along with the inflammatory response, and the skin barrier proteins (Filaggrin and Involucrin) and inflammatory cytokines (TNF-α, IL-31, IL-13) seem to be key players in the pathogenesis of AD in dogs." (PMID 34075152, 2021).
helminth infection (189 papers, 2006 to 2026). "Worm-resistant domestic sheep have an upregulated IL-4 response when compared to susceptible sheep and similarly, IL-13 and IL-5, two other Th2-associated cytokines, have been negatively associated with worm infections in humans." (PMID 39963298, 2025). "ILC2s have been implicated in immune responses to extracellular helminth infections via the secretion of the type 2 cytokines IL-4, IL-5, IL-9 and IL-13." (PMID 40591723, 2025). "This is different when we compare it with other helminth infections; for example, during schistosomiasis, IL-4/IL-13, specifically produced by Th2-CD4+ cells, was associated with protection." (PMID 38392907, 2024). "In A. suum, the helminth-infection hallmark cytokines IL-13, IL-25 and IL-33 were identified as potential targets of lin-4-5p and let-7-5p, miR-5350d-5p and miR-87a/b-3p, respectively." (PMID 38172997, 2024). "IL-5 regulates B-cell antibody production and enhances IgA production from B-cells, while IL-5 and IL-13 are implicated in allergic inflammation and protection against helminth infection." (PMID 35707544, 2022). "AAMs are one of the most important sources of IL-4 and IL-13 during helminth infection, and liver fibrosis is associated with AAMs infiltration." (PMID 34733286, 2021). "The immunological hallmark of helminth infections is their ability to induce Th-2 associated immune responses characterized by the presence of the IL-4, IL-5, IL-9, IL-10, and IL-13." (PMID 35087402, 2021). "Some previous studies have shown that Th2 immune responses associated with helminths infection were characterized by the induction of IL-4, IL-13, IgG, IgG1, and IgE antibodies in rats, and the generation of IL-3, IL-4, IL-5, and IL-13 in mice." (PMID 32971770, 2020). "The previous research of defense mechanisms against helminths infections is typically associated with a type 2 immune response characterized by the expression of the cytokines IL-3, IL-4, IL-5, IL-9, IL- 10, and IL-13." (PMID 32243446, 2020). "Helminths infection elicited strong Th2 cell responses associated with significant productions of interleukin (IL)-4, IL-5, IL-9, IL-10, IL-13, IL-25, and IL-31." (PMID 32971770, 2020). "In helminth infections, TCRγδ+ cells are associated, through the secretion of IL-4, IL-5 and IL-13, with the development of a Th2 response." (PMID 33023672, 2020). "We stimulated human monocyte-derived macrophages with zinc sulfate, in combination with 3 different concentrations of IL-4 or IL-13 (cytokines associated with a Th2 response to helminth infection)." (PMID 31841569, 2019). "Helminth infections are typically associated with Type 2 cytokine responses with elevated levels of IL-4, IL-5 and IL-13." (PMID 30897083, 2019). "Helminth infection in the intestine was associated with a significant upregulation of IL-4 and IL-13 expression in lung tissue." (PMID 31673002, 2019). "Helminth infections strongly induce Th2-skewed responses associated with cytokines (e.g., IL-4, IL-5, and IL-13), mastocytosis, eosinophilia, and antibody class-switching producing IgE [reviewed in Ref." (PMID 29670630, 2018). "Th2 associated cytokines including IL-4 and IL-13 are upregulated in both helminth infections and allergic disorders." (PMID 28494800, 2017). "IL-13 is necessary for the elimination of the parasite from the gastrointestinal tract, and transferring ILC2s into IL-13-deficient mice shows that IL-13 production by ILC2s is sufficient to resolve helminth infection." (PMID 27774092, 2016). "Later, the transfer of ILC2s into IL-13-deficient mice, which displayed reduced T cell responses following helminth infection, was shown to restore Th2 cell responses in vivo." (PMID 25088770, 2014). "IL-13 is a signature cytokine of the helper T cell type 2 (TH2) pathway which underlies host defense to helminthic infection and activates production of IgE in both parasitized populations and in urban settings after allergen exposure." (PMID 22574126, 2012).
helminth infection (continued). "Induction of goblet cell hyperplasia is associated with TH2 immune responses, which in helminth infections are controlled primarily by IL-13, and also IL-4." (PMID 18373844, 2008). "However, one has to keep in mind that systemic modulation of IL-4 as well as IL-13 signaling can also cause severe side-effects like a propensity towards helminth infections or acute gastric mucosal injury." (PMID 33450900, 2021). "Furthermore, worm infections have been associated with a reduced progression of colitis through the increase of IL-4/IL-13 and the upregulation of AAM." (PMID 28951733, 2017). "Interleukin 13 (IL-13) is a key factor in fibrotic disease associated with helminth infection, but it is unclear whether it plays a similar role in radiation-induced lung fibrosis." (PMID 28004808, 2016). "The cytokine most associated with efficient clearance of helminth infection is IL-13." (PMID 25474738, 2014). "Our evaluation of IL13 variation has demonstrated TH2 pathway genes shown to carry variants that impact on atopic disease are good candidates to evaluate determinants of host immunity to helminthic infections." (PMID 22574126, 2012). "Polarized Th-2 immune activation associated with helminthic infection modifies cytokine profiles, whereby anti-inflammatory IL-4, IL-10 and IL-13 protect vessel walls from oxidized LDL-induced monocyte injury in the endothelium, and downregulate fibrinogen synthesis." (PMID 19668697, 2009). "During helminth infection, interleukin-13 (IL-13) or IL-4 drive a 10-fold expansion of tuft cells to promote helminth clearance." (PMID 41739917, 2026). "In the gut, their classical role was attributed to protection against parasitic infections—a notion supported by the Th2-dominated responses (IL-4, IL-5, IL-13) and elevated eosinophil counts observed in helminthiasis." (PMID 40860650, 2025). "In helminth infections, the immune response is predominantly skewed toward a Th2 profile, characterized by the activation of IL-4, IL-5, and IL-13 pathways, increased eosinophil recruitment, and IgE class-switching." (PMID 41227415, 2025). "In helminth infections, antigen proteins activate Th2 to stimulate the secretion of IL-4 and IL-13, which will stimulate the secretion of Tregs and IL-10." (PMID 41239264, 2025). "Our findings unequivocally demonstrate an intrinsic requirement for IL-17RB in ILC2s to foster proliferation and induce IL-13 expression upon succinate-mediated circuit stimulation, as well as to mount effective responses to clear helminth infections." (PMID 40074948, 2025). "iILC2s serve as early producers of IL-13 and IL-4 during helminth infection (day 5 post-infection), preceding cytokine secretion by nILC2s, and can migrate from gut to lung to initiate anti-helminth immunity." (PMID 41041315, 2025). "Concurrently, the ILC2INFLAM produces type 2 inflammatory cytokines IL-5 and IL-13, which recruit eosinophils and exert dual immunomodulatory effects: conferring protection against helminth infections while promoting the pathogenesis of allergic diseases." (PMID 41041315, 2025). "Typically, worm infections increase Th2 cytokines, such as IL-4 and IL-13, while decreasing Th1 cytokines like IL-12 and IFN-γ." (PMID 41268546, 2025). "Studies measuring macrophage activity through IL4/IL13 have demonstrated their anti-inflammatory function in regulating helminth infections." (PMID 39057830, 2024). "Our use of a magnetic microrheometer to directly measure the compliance of intestinal mucus after IL-13 treatment is the first approach to quantify the biophysical effects of helminth infections." (PMID 38721267, 2024). "During helminth infections, eosinophils support type 2 immunity by secreting IL-4, IL-5, IL-10, and IL-13." (PMID 39140728, 2024).
helminth infection (continued). "Previous work showed that IL-33, a cytokine upregulated in inflammatory bowel disease and helminth infections like N. brasiliensis, induces intestinal goblet cells and Muc2 expression in mice through IL-13 production by innate lymphoid cells." (PMID 38721267, 2024). "Gastrointestinal DCLK1+ tuft cells constitutively express IL-25, and its expression is further increased after helminth infection, leading to IL-13 secretion by type 2 innate lymphoid cells (ILC2s)." (PMID 38061015, 2024). "Conversely, Th2 cells and their signature cytokines (IL-4, IL-5, and IL-13) are largely characterized by their role in helminth infection or allergic responses and the promotion of IgE-mediated eosinophilic responses." (PMID 38672668, 2024). "It was previously demonstrated that the Th2 effector cytokine, IL-13, is the predominant driver of the local intestinal mucus response in a helminth infection." (PMID 39596084, 2024). "Immunity to worm infections is mediated by the cytokine IL-13, which can be secreted by ILC2 or Th2 cells and induces a ‘weep and sweep’ reaction to expel the parasites." (PMID 39632879, 2024). "Gastrointestinal DCLK1+ tuft cells constitutively express IL-25, and its expression is further increased after helminth infection, leading to IL-13 secretion by ILC2s." (PMID 38061015, 2024). "Type 2 cytokines, especially IL-13, produced by activated ILC2s promote M2 polarization, resulting in protective immunity in a cerebral malaria model and helminth infection, or induce allergic inflammation in fungal infection." (PMID 36941691, 2023). "Ang4, Clca1, and Retnlb are goblet-cell associated genes that are induced during immune responses, such as bacterial and helminth infections, and are typically stimulated by type 2 and 3 immune cytokines such as IL-4/IL-13 (type 2) and IL-22 (type 3)." (PMID 37869014, 2023). "During helminth infection, IL-25 derived from tuft cells induces IL-13 secretion from ILC2s, which leads to epithelial remodeling by increasing the number of tuft and goblet cells." (PMID 36941691, 2023). "Further, hypercontractility of smooth muscle cells evoked by IL-4 and IL-13 was shown to be dependent on STAT6 in helminth infection." (PMID 37018382, 2023). "ILC2s produce type 2 cytokines, including IL-4, IL-5, and IL-13, and play a critical role in allergic and helminth infections." (PMID 37235324, 2023). "SP-A and SP-D enhanced IL-4/IL-13-dependent M2 macrophage activation, promoting lung repair during helminth infection." (PMID 37234176, 2023). "IL-4 and IL-13 are produced during helminth infections, which in turn activates the IL-4R/STAT signalling pathway." (PMID 37705099, 2023). "During helminth infections, lamina propria macrophages produce various factors such as IL-4, IL-13, IL-10, arginase-1 (Arg-1), chitinase-like protein (Ym1), and resistin-like alpha." (PMID 38203591, 2023). "On the other hand, the alternative activation of macrophages is stimulated by macrophage colony-stimulating factor (M-CSF1, CSF1), IL-4, IL-10, transforming growth factor β (TGF-β), IL-13, and fungi or helminth infections, and leads to the M2 phenotype." (PMID 37958467, 2023). "TCs release IL-25 upon helminth infection and activate ILC2s to secrete IL-13, while IL-13 promotes the ISCs differentiation into TCs and goblet cells." (PMID 38283340, 2023). "During helminth infection, IL-13 stimulation of IECs drives epithelial cell changes, including goblet and tuft cell hyperplasia similar to that observed in the Hoil1−/− mice." (PMID 35534698, 2022). "After helminth infection, IL-25 is produced by tuft cells, which further activates group 2 innate lymphoid cells (ILC2s) to secrete IL-13, which acts on crypt progenitor cells to promote the differentiation of tuft and goblet cells." (PMID 36232438, 2022). "iILC2 cells express more IL-25R and develop into nILC2-like cells, producing IL-5 and IL-13 after stimulation with IL-33 during worm infection." (PMID 35707544, 2022).